PRDX2 (peroxiredoxin 2)
Diseases named in the same sentence as PRDX2 in open-access papers (continued):
Sharing a sentence is not in itself a finding about the gene and the disease.
neurodegenerative disease (4 papers, 2014 to 2026). A disorder of the central nervous system characterized by gradual and progressive loss of neural tissue and neurologic function. "The increased expression of GLUT1, HK1, and PRDX2 in microglia suggests a potential mechanism for metabolic dysregulation and oxidative stress in response to inflammatory stimuli in neurodegenerative disease processes." (PMID 40888599, 2026). "Further studies to validate the effect of PRDX2 on PD patients with LRRK2 kinase mutations and to investigate the neuroprotective effects of Chetomin in other neurodegenerative diseases will be warranted." (PMID 32990658, 2020). "PRDX2 has been reported contributing to neuroprotection and was proposed for treatment for neurodegenerative diseases." (PMID 24695528, 2014).
cardiovascular disease (2 papers, 2022 to 2025). "The Prdx family has emerged as a key player in the development of cardiovascular disease, particularly Prdx2, which effectively scavenges cellular ROS and reduces apoptosis." (PMID 39763059, 2025).
hematological disease (2 papers, 2022 to 2025). "This potential connection between PRDX2 and RBC size variability could pave the way for further research into its role in hematological disorders, particularly those involving oxidative stress." (PMID 40128671, 2025).
adenocarcinoma (1 paper, 2020). A common cancer characterized by the presence of malignant glandular cells. "However, only PRDX2, PRDX3, and PRDX6 expression was associated with worse OS in adenocarcinoma patients." (PMID 32908916, 2020). "Furthermore, the high levels of PRDX2 were also related to bad OS in 719 adenocarcinoma patients (P < 0.0001) (363 samples with low PRDX2 expression and 356 samples with high PRDX2 expression)." (PMID 32908916, 2020). "Moreover, PRDX2 and PRDX6 exhibited stronger connections than PRDX3 in adenocarcinoma patients." (PMID 32908916, 2020).
brain diseases (1 paper, 2017). "In the present study we characterized for the first time the expression of the antioxidative enzyme PRDX2 in CNS autopsy tissue of patients with MS and patients without reported or neuropathologically detectable brain diseases (controls)." (PMID 28375164, 2017).
cardiac disease (1 paper, 2023). "We found that the downregulation of the PRDX2 gene in elderly patients implies an added risk of cardiac disease in this age group." (PMID 37365269, 2023).
mitochondrial disease (1 paper, 2025). "A combined urinary biomarker panel—including stress markers (GDF15, CYCS, and PRDX2), immune effectors (MPO and C4A), ECM proteins (COL1A1 and CCN2), and selected amino acids—could support diagnosis, patient stratification, and longitudinal monitoring in mitochondrial disease." (PMID 41373442, 2025).
psychiatric disorder (1 paper, 2013). A disorder characterized by behavioral and/or psychological abnormalities, often accompanied by physical symptoms. "The differentially expressed proteins included those previously implicated in psychiatric disorders, such as ALDOC, ENO1, and PRDX2." (PMID 23408933, 2013).
PRDX2 also shares sentences with these, for which no sentence is quoted: sickle cell disease (4 papers); type 2 diabetes (4); esophageal carcinoma (3); esophageal squamous cell carcinoma (3); colon adenocarcinoma (2); head and neck cancer (2); infectious disease (2); leukemia (2); lung squamous cell carcinoma (2); schistosomiasis (2); serous ovarian cancer (2); stomach cancer (2); thyroid cancer (2); acute GVHD (1); aortic aneurysm (1); artery thrombosis (1); autoimmune disease (1); autoimmune polyendocrinopathy candidiasis ectodermal dystrophy (1); bipolar II disorder (1); bowel obstruction (1); breast carcinoma in situ (1); breast invasive carcinoma (1); cataract (1); cervix (1); cholangiocarcinoma (1); Coma (1); cyst (1); depression (1); diabetic foot ulcer (1); diabetic retinopathy (1).
A further 42 diseases each share a sentence with PRDX2 in 1 paper.